TSPAN19 (tetraspanin 19)
Tractability: Antibody: UniProt predicts a signal peptide or a membrane-spanning region; its Gene Ontology location is reachable by antibodies, with medium confidence.
Gene: Protein-coding gene on chromosome 12 (85,014,311 to 85,036,277, reverse strand). Ensembl gene ENSG00000231738.
Subcellular location: Membrane
Gene Ontology:
Cellular component: plasma membrane; membrane
Genetic constraint (gnomAD): Loss-of-function variants: 15 observed, 10.49 expected, observed/expected ratio (o/e) 1.43, 90% interval 0.94 to 1.91. The upper end of that interval is the gene's LOEUF score, 1.91, which puts it in group 6 of 6, group 1 being the genes least tolerant of losing a copy. Missense variants: 90 observed, 81.32 expected, observed/expected ratio (o/e) 1.11, 90% interval 0.93 to 1.32. Synonymous variants: 30 observed, 27.67 expected, observed/expected ratio (o/e) 1.08, 90% interval 0.81 to 1.47.
Homologues: Orthologues: chimpanzee TSPAN19 (99% identical), macaque TSPAN19 (94% identical), dog TSPAN19 (77% identical), rabbit TSPAN19 (77% identical), pig TSPAN19 (73% identical). Paralogues in human: CD82 (27% identical), CD37 (26% identical), CD53 (21% identical), CD63 (21% identical), TSPAN33 (21% identical), TSPAN5 (21% identical), TSPAN1 (21% identical), TSPAN11 (20% identical), TSPAN17 (20% identical), TSPAN7 (20% identical), CD151 (19% identical), TSPAN10 (19% identical), and 20 more.
Diseases named in the same sentence as TSPAN19 in open-access papers:
TSPAN19 is named in the same sentence as 3 diseases in open-access papers, as found by Europe PMC text mining. Sharing a sentence is not in itself a finding about the gene and the disease. The quoted sentences say what the papers report.
mastitis (1 paper, 2017). Inflammation of breast tissue during lactation or postpartum due to an obstructed duct or infection. "The TSPAN19 gene was identified as one of the candidate genes affecting mastitis in dairy cattle." (PMID 28129396, 2017).
TSPAN19 also shares sentences with these, for which no sentence is quoted: infection (1 paper); tumor (1).